IL2 (interleukin 2)
Diseases named in the same sentence as IL2 in open-access papers (continued):
Sharing a sentence is not in itself a finding about the gene and the disease.
endometriosis (30 papers, 2009 to 2025). The growth of functional endometrial tissue in anatomic sites outside the uterine body. "Given the significant heterogeneity and single SNP results in the IL-2 analysis, the reported association between IL-2 and endometriosis should be interpreted with caution." (PMID 39766252, 2024). "Elevated levels of IL-9 were also causally associated with endometriosis, while a potential positive association was detected for IL-2 with endometriosis, albeit using less reliable measures." (PMID 39766252, 2024). "Their data showed an increase of TH1–TH2 ratio caused by the increased amount of TNF-α and IL-2 in women with severe endometriosis." (PMID 34639133, 2021). "Finally, we found that IL-2 was causally associated with endometriosis via the WMe method with an odds ratio of 1.18." (PMID 39766252, 2024). "Endometriosis is believed to be associated with dysfunction of the lymphocyte population and cytotoxicity of natural killer (NK) cells, induced by the production of interleukin-2 (IL-2)." (PMID 36313261, 2022). "The interleukin IL-4/IFN-γ, IL-10/IFN-γ, and IL-4/IL-2 ratios are higher in women with endometriosis, probably in the late stage." (PMID 40508002, 2025). "There was no statistically significant heterogeneity in any 2-SMR analyses (p > 0.05), except for IL-2 and endometriosis, which displayed statistically significant heterogeneity via the IVW method." (PMID 39766252, 2024). "Higher levels of serum IL-37 and IL-10, and significantly lower levels of serum IL-17A and IL-2 were detected in patients with endometriosis." (PMID 39595927, 2024). "In Bonferroni-corrected leave-one-out analyses, omitting single SNPs did not achieve statistical significance for exposures associated with PCOS (MCP-1/CCL2: p > 3.85 × 10−3, 0.05/13) or endometriosis (IL-2: p > 0.01, 0.05/5; IL-9: p > 8.33 × 10−3, 0.05/6)." (PMID 39766252, 2024). "Cytokines such as IL-37, IL-17A, IL-10, and IL-2 play essential roles in modulating immune responses in endometriosis." (PMID 39595927, 2024). "The significant enhancement of lymphocyte T and NK cell cytotoxicity was observed in all doses of IL-2 against both Daudi and K562 cells in the endometriosis group." (PMID 36313261, 2022). "In the secretory phase, IL-2 and IL-4 expression decreased by 64.3% and 82.1%, respectively, in the non-endometriosis endometrium, compared to the eutopic endometrium." (PMID 35269619, 2022). "Only IL-2 and losartan treatment have been tested in an endometriosis rat model with promising results." (PMID 35628346, 2022). "It was found that the expression of CD28+ was higher in the women with endometriosis after being stimulated with IL-2." (PMID 36313261, 2022). "Expression of cytokines IL-2, IL-6, IL-10, and IL-15 was lower in endometriosis lesions than in eutopic endometrium in the secretory phase." (PMID 35269619, 2022). "Although an increase in the CD107a + CD56+ cell percentage after treatment with IL-2 was observed in the endometriosis group, the amount of IFN-γ produced by CD107a + CD56+ cells was slightly decreased in this group." (PMID 34616540, 2021). "This study aimed to evaluate the level of the peripheral NK cell surface marker CD107a in endometriosis in the presence of IL-2 stimulation." (PMID 34616540, 2021). "The levels of CD107a were significantly enhanced in peripheral blood taken from women with endometriosis after treatment with IL-2." (PMID 34616540, 2021). "We observed that, after treatment with IL-2, the expression of CD107a was significantly increased in the endometriosis group compared to the control group." (PMID 34616540, 2021). "We can also understand why a therapy based on the recombinant IL-2, a Th1 cytokine, which was launched ostensibly based on its putative anti-inflammatory propensity, failed in endometriosis." (PMID 33381124, 2020).
endometriosis (continued). "It has been also reported that IL-2 resulted in the activation of host immune reactivity and further resulted in the reduction of endometrial implants in an experimental rat model of endometriosis." (PMID 31540116, 2019). "Recently, a study demonstrated that activation of leucocytes with IL-2, induced a persistent reduction of endometriosis lesions in female rats." (PMID 26318622, 2015). "Levels of IL-2 are increased in the peritoneal fluid of mice with endometriosis suggesting a role of this cytokine in infertility related to this disease." (PMID 25915402, 2015). "IL-2 was increased in the peritoneal fluid of non pregnant mice compared to the pregnant ones in the group with endometriosis." (PMID 25915402, 2015). "Velasco and Cols found that treatment of female rats with endometriosis with IL-2 (two doses given by the i.p. route) resulted in the activation of leucocytes and a significant reduction in the size of endometriotic lesions compared to the untreated group." (PMID 26318622, 2015). "Based on the reviewed data, the objective of the present work was to evaluate the effect of endometriosis on fertility and the levels of the IL-2 and IFN-γ in the peritoneal fluid in a mouse model." (PMID 25915402, 2015). "While IFN-γ increased in non pregnant versus pregnant mice in the sham group, IL-2 was increased in non pregnant mice in the endometriosis group." (PMID 25915402, 2015). "IL-2 may also play a role in menstrual disorders, particularly in conditions like endometriosis and premenstrual syndrome." (PMID 40028534, 2025). "One article showed that interleukins IL-2 and IL-27 work together to enhance the growth and invasion of endometriotic stromal cells by regulating the balance between IFNγ and IL-10 in the context of endometriosis." (PMID 39767772, 2024). "A second limitation pertains to the IL-2 analysis, which was only significantly associated with endometriosis via the WMe method but not when using the primary IVW analysis." (PMID 39766252, 2024). "However, a recent study reported that IL-2 levels were significantly lower in serum but higher in peritoneal fluid in women with varying stages of endometriosis compared with control women." (PMID 39766252, 2024). "Although IL-2 demonstrated an association with endometriosis using WMe analysis, this did not fulfil the MR quality assessments due to significance in single SNP analysis and heterogeneity." (PMID 39766252, 2024). "However, the role of IL-2 in the development of endometriosis is not well understood, as research findings are inconsistent." (PMID 39767772, 2024). "IL-2 stimulated NK cells which regulate the production of lymphokine-activated killer cells, indicating an increased potential against resistant tumor cells, including endometrial cells, both in-vitro and in women with endometriosis." (PMID 36313261, 2022). "Furthermore, peritoneal NK cells and DCs were enhanced in rats with endometriosis treated with IL-2, and a greater number of activated lymphocytes, macrophages, NK cells, and DCs was observed in the implants." (PMID 35628346, 2022). "PBMCs were evaluated in the endometriosis group and the control group prior to IL-2 treatment." (PMID 34616540, 2021). "The role of IL-1β and IL-2 in the endometriosis development is still unclear." (PMID 34639133, 2021). "In addition, there was a significant difference in CD107a expression in the endometriosis group before versus after stimulation with IL-2." (PMID 34616540, 2021). "In addition, there was a significant difference in CD107a expression in the endometriosis group before versus after stimulation with IL-2 (p < 0.01)." (PMID 34616540, 2021). "On this basis, is possible that IL-2 activated NK cells could form the basis of a new treatment alternative for patients with endometriosis." (PMID 26318622, 2015).
endometriosis (continued). "However, one SNP was individually associated with endometriosis in the IL-2 (rs4634519, p = 0.0082; p < 0.01, 0.05/5), but not IL-9 analysis (p > 8.33 × 10−3, 0.05/6)." (PMID 39766252, 2024). "The expression of IL-2, IL-17A, and EGF was higher in the non-endometriosis group than in the eutopic endometrium group." (PMID 35269619, 2022). "Interferon alpha and gamma responses, TGF-beta and IL-2 STAT5 signaling, and complement pathways were upregulated in endometriosis consistently across most menstrual phase and disease stage stratifications (FDR < 0.05)." (PMID 35069565, 2021). "The results of the present study show for the first time that PF from women with advanced endometriosis displays immunomodulatory activity toward both unstimulated and CD3/CD28/IL-2-stimulated CD4+ T cells." (PMID 34360900, 2021). "Nevertheless, contradictory results for levels of IL-10, IL-1β, IL-2 and TNF-α in the peritoneal fluid of women with endometriosis has been also reported." (PMID 34639133, 2021). "Indeed, in endometriotic lesions, the levels of IFN-γ and IL10 and the ratios of IL4/IFN-γ, IL4/IL2 IL10/IFN-γ, and IL10/IL2 are significantly elevated in the peritoneal fluid of endometriosis patients compared to healthy controls." (PMID 35935991, 2022). "It was also found that there was a significant increase of CD3-CD28+ after treatment with IL-2 only in the healthy control but not in women with endometriosis." (PMID 36313261, 2022). "In this study, it was also found that there was no change in CD160 expression after being treated with IL-2 in both the endometriosis and control groups." (PMID 36313261, 2022). "In conclusion, stimulation with IL-2 increased the percentages of CD107a + CD56+ cells among PMBCs from women with endometriosis but did not increase the levels of the cytokines produced by these cells, TNF-α and IFN-γ." (PMID 34616540, 2021). "IL-2 was increased in the peritoneal fluid of non pregnant compared to pregnant mice with endometriosis but no statistical differences were seen within the sham group." (PMID 25915402, 2015). "The role of IL-2 in the pathogenesis of endometriosis is not clearly defined." (PMID 35805112, 2022). "Pregnancy rate is decreased in the mouse model of endometriosis, and the level of IL-2 was increased in nonpregnant mice in the endometriosis group, which suggest that the high level of IL-2 may lead to infertility." (PMID 33224295, 2019). "To see whether the PF from the patients with endometriosis and the control subjects may affect in vitro generation of Treg and Th17 cells we evaluated specific phenotype changes of the unstimulated and CD3/CD28/IL-2-stimulated CD4+ T cells following their 5-day culture." (PMID 34360900, 2021). "In our study, the analysis of the correlations regarding Ucn1 serum concentrations and cytokines levels including IL-2, IL-4, IL-6, IL-10 and IFN-gamma also brought not so many significant dependencies among women with endometriosis and healthy controls." (PMID 37175494, 2023). "Since high levels of IL-2 and IFN-γ are related to infertility and reproductive organs are bathed in the peritoneal fluid we evaluated the levels of these cytokines in pregnant and non pregnant mice with and without endometriosis." (PMID 25915402, 2015).
Insulin resistance (29 papers, 2012 to 2025). Increased resistance towards insulin, that is, diminished effectiveness of insulin in reducing blood glucose levels. "The recruitment of macrophages is the main characteristic of inflammation in white adipose tissue and promoted the secretion of TNF-α, IL-2, and IL-6 which cause insulin resistance." (PMID 36647430, 2023). "Further, this elevation of IL-2 is associated with insulin resistance as well as with several important inflammatory markers." (PMID 33004937, 2020). "Since insulin resistance is a metabolic state linked with an increased oxidative stress and inflammation, serum total antioxidative status and serum interleukin IL-2 concentration were measured." (PMID 23065486, 2012). "Furthermore, this elevation of IL-2 is associated with insulin resistance and several inflammatory markers." (PMID 38533504, 2024). "IL-2 could be characterized as an inflammatory cytokine, as it is associated with markers of inflammation as well as insulin resistance in overweight and obese individuals." (PMID 33917916, 2021). "Furthermore, our data show a significant positive association of IL-2 expression in the AT with insulin resistance signatures including FBG and HbA1c in overweight and obese individuals." (PMID 33004937, 2020). "The administration of HCD in piglets has been associated with hepatic steatosis, insulin resistance, and hepatic inflammation, including increased myeloperoxidase activity and expression of proinflammatory cytokines and chemokines, particularly IL-2, CXCL2, TNFα, and IL-6." (PMID 23565157, 2013). "An upregulation of adipose tissue-associated IL-2 expression in overweight or obese individuals contributes to an increased expression of metabolic parameters, such as C-reactive protein and triglyceride levels, which increases the risk of the development of insulin resistance." (PMID 40863244, 2025). "The recent preliminary findings from our group found that consumption of 3 servings/day of low-fat dairy products normalized IL-2 production from PBMC in a swine model of insulin resistance, suggesting improved T cell function as compared to controls." (PMID 35252310, 2022). "PTSD is associated with low-density lipoprotein-cholesterol, cortisol, interleukin (IL)-2, IL-6, IL-8, leptin, insulin resistance, and tumor necrosis factor (TNF)-α9–12." (PMID 33674663, 2021). "IL-2 production is involved in insulin resistance onset, followed by macrophages’ activation and cytokines’ secretion." (PMID 34360753, 2021). "IL-2 has been directly positively correlated with increased levels of insulin resistance, and higher sera soluble IL-2 receptor (sIL-2r) levels were observed in T2DM patients as well." (PMID 34360753, 2021). "In both high-fed diet (HFD)-induced obese mice and mice heterozygous for the yellow spontaneous mutation (Ay/a), injection of IL-2 in complex with IL-2 antibody (mAb) increased the fraction of Treg cells in VAT and spleen, and reduced insulin resistance." (PMID 30323806, 2018). "It has also been reported that T-cell-derived transforming growth factor-β (TGF-β), interferon γ (IFN-γ), granulocyte-macrophage colony-stimulating factor (GM-CSF) and interleukin-2 (IL-2) cytokines are involved in the immune-mediated destruction of diabetic β cells, leading to insulin resistance." (PMID 37108143, 2023). "The levels of FBG, TC, TG, and other indicators were significantly decreased, indicating that the decreased IL-2 expression may be related to hyperglycemia and insulin resistance." (PMID 35873798, 2022). "The augmented levels of INF-γ were linked to higher levels of insulin resistance, and HMGB1 and IL-2 co-treatment could increase the release of IFN-γ in PBMCs and NK-cells, as already reported." (PMID 34360753, 2021).
Insulin resistance (continued). "Adipose tissue-associated IL-2 is also associated with overexpression of a variety of inflammatory markers, such as IL-8, IL-12a, IL-1β, C-C motif chemokine ligand 5 (CCL5), CCL15, TLR2, and an inflammatory macrophage marker (CD11c), inducing inflammation and insulin resistance." (PMID 40863244, 2025). "Thus, IL-2 may represent as a novel biomarker for progression of metabolic inflammation and insulin-resistance." (PMID 33004937, 2020). "Obese individuals with elevated levels of IL-2 gene expression in the AT showed a strong positive correlation with FBG and HbA1c which implies that increased IL-2 expression might be linked to hyperglycemia and/or insulin resistance." (PMID 33004937, 2020). "According to a hypothesis presented by Penntinen, an increased plasma IL-2 concentration brings about a reduction of bioavailability of insulin-like growth factor-1, by reducing the production of androgenic hormones, thus contributing to insulin resistance." (PMID 23065486, 2012). "In contrast, Treg augmentation through IL‐2–IL‐2 antibody complexes or adoptive transfer of lymphoid Tregs improves glucose tolerance, suggesting a protective role for VAT Tregs in insulin resistance." (PMID 32463116, 2020). "It has been reported that insulin resistance and cytokines such as TNF-α, IL-1, IL-2, IL-6, PAF raise serum triglyceride levels while reduce total and HDL-cholesterol levels." (PMID 24772131, 2014). "Significant increases in the production of IL-2, IL-8, IL-12A, CCL5, CCL19, CCR2, CCR5, TLRs, and other variables in the AT suggest that these elements may interact to induce insulin resistance in this population." (PMID 37237937, 2023).